TLR2 (toll like receptor 2)
Diseases named in the same sentence as TLR2 in open-access papers (continued):
Sharing a sentence is not in itself a finding about the gene and the disease.
infection (continued). "We used the same doses of bacteria as used for analysis of infection burdens in the tlr2 mutants." (PMID 36741407, 2022). "Alternatively, these PE/PPE proteins may have independent roles in TLR2 signaling, either activating or inhibiting TLR2 signaling depending on the particular stage of infection or features of the tissue microenvironment." (PMID 35467412, 2022). "In addition, the role of heterodimeric complexes of TLR2 during the infection of BMDCs demonstrate that, in KO cells for TLR2, the infection was drastically reduced compared with wildtype (WT) cells, suggesting that TLR2 facilitates DENV infection." (PMID 35632732, 2022). "TLR2 is also expressed in neurons, and prolonged infection with SARS-CoV-2 may induce neuronal TLR2 activation in the brain." (PMID 35396576, 2022). "Similarly, production of nitric oxide (NO) 24 h post-infection was also dependent on the presence of TLR2 and TLR4." (PMID 35899053, 2022). "Despite these findings, the conclusion that TLR2 exerts a significant effect on host anti-staphylococcal defenses has not been fully supported by all studies, with results varying based on tissue specificity and the infection model (32, –, 36, 38, 55)." (PMID 36226943, 2022). "Interestingly, our observed protective phenotype with the rh-gal-9 treatment is comparable to that observed by other groups who have administered multiple treatments of TLR2 inhibitors post infection." (PMID 36325323, 2022). "To determine whether the loss of TLR2 and TLR9 alters infection-associated trabecular bone loss, we first performed baseline analyses of uninfected mice to rule out underlying differences in trabecular bone volumes within groups." (PMID 36226943, 2022). "The up-regulatory effect on MyD88 and TRIF may be the result of direct viral interaction or the up-regulation effect on cell-membrane- (TLR2 and TLR4) and endosomal-associated (TLR3, TLR8, and TLR9) TLRs induced by single-PDCoV infection." (PMID 36376395, 2022). "Genetic deletion of ppe51 from Mtb resulted in the enhanced activation of TLR2 signaling during infection, enhanced phosphorylation of MAPK Erk1/2 and accumulation of ROS and proinflammatory cytokines, increased autophagy, and reduced bacterial survival in macrophages." (PMID 35467412, 2022). "For instance, LTA, a membrane-anchored teichoic acid especially found to be indispensable in Staphylococcus aureus, has been shown to exert host immune recognition and stimulation upon infection through toll-like receptor 2 (TLR2), a receptor either pairing with TLR1 or TLR6." (PMID 35857130, 2022). "Also, in similar studies with H. contortus artificial infections, a higher expression of the TLR2 gene was observed in abomasal tissue of Morada Nova-resistant lambs." (PMID 36140716, 2022). "In our analysis of differential proteomic changes in MAP-resistant cows, a term we use to describe cows that are less susceptible to infection with MAP, we observed a significant increase in the expression of TLR2, BoLA-DRB3, and BoLA-DRA in PBMC after co-incubation with MAP in vitro." (PMID 36295826, 2022). "However, since both S. aureus and S. epidermidis can activate the extracellular TLR2 to initiate the skin’s immune response against bacterial invasion and infection, another mechanisms must be involved in differentiation between S. aureus and S. epidermidis." (PMID 35281009, 2022). "TLR6 may form heterodimers with TLR2, which can recognize viral proteins and enhance infection, leading to increased TLR6 expression." (PMID 36171749, 2022). "Infection with L. infantum and L. mexicana initiates TLR2/9 activation leading to host protective immune response, while infection with L. major, L. donovani and L. amazonensis trigger either a TLR2‐ /9‐related protective or non‐protective immune responses." (PMID 35119120, 2022). "TLR-2 has been shown to be important for late stages of infection when compared to TLR-4." (PMID 36121578, 2022).
infection (continued). "The microbiota-derived metabolites can activate TLR2 on glial cells, which results in an increased IL-22 secretion by innate lymphoid cells (ILC)-3 to provide protection against inflammation or pathogenic infection." (PMID 35626706, 2022). "Considering that H37Ra infection was found to suppress the expression of PPARγ, it seemed that TLR2 signaling could downregulate the expression of PPARγ." (PMID 35432274, 2022). "Studies regarding oncology and infection revealed that TLR2 may be involved in M2 macrophages’ polarization." (PMID 35954209, 2022). "Also, TLR2 was significantly expressed in spleen and liver of infected WT mice 4 weeks post‐infection with high inflammatory infiltration and reduced parasite burden when compared to that TLR2‐/‐ mice." (PMID 35119120, 2022). "Based on in vivo experiments with another Gram-negative bacteria, Porphyromonas gingivalis, it has been shown that during infection, platelets interact with neutrophils forming heterotypic aggregates in a TLR2-dependant fashion and that TLR2 promotes the aggregation of platelets." (PMID 35402556, 2022). "In addition, sequential infections in outbred SPexp mice resulted in an increased prevalence of TLR2- and TLR4-expressing leukocytes." (PMID 35878936, 2022). "In addition, transcriptome analysis showed that the number of up-regulated and down-regulated genes in response to infection was greatly diminished in infected tlr2 mutant zebrafish compared to their heterozygous sibling controls." (PMID 35205112, 2022). "Infection with MG increased TLR2 levels and thereby activated the NF-κB pathway." (PMID 36139393, 2022). "Interestingly, polarization to the Th2 -biased antibody response was also seen in a TLR2/MYD88-dependent manner, and the capability of this axis to cause ADE in subsequent heterotypic infections was shown." (PMID 35632732, 2022). "However, low-dose infection of Mtb in mice defective for TLR2 demonstrated little difference in inflammation, granuloma formation, or bacterial survival." (PMID 35467412, 2022). "Next, we then assessed the survival of C. neoformans Δsgl1-vaccinated and unvaccinated C57BL/6 or TLR2−/− mice against a WT challenge, and we found that vaccinated TLR2−/− mice fully succumbed to fatal WT infection at a similar rate to unvaccinated TLR2−/− mice." (PMID 36229573, 2022). "Although tlr2 plays a protective role in the host defense against different NTM species, the underlying mechanisms may be different in infections by different mycobacterial species." (PMID 36741407, 2022). "To test whether the loss of TLR2 and TLR9 reduces infection-associated osteoclastogenesis, we assessed osteoclast abundance relative to bone volume in the trabecular region using histomorphometry." (PMID 36226943, 2022). "Taken alongside data showing that TLR2- and TLR9-deficient osteoclast precursors undergo osteoclastogenesis upon intracellular infection with S. aureus, these data suggest that TLR2- and TLR9-independent pathways have the potential to modulate osteoclastogenesis during osteomyelitis." (PMID 36226943, 2022). "Altogether, these findings illuminated that a long-term infection with LTA might gradually weaken the stimulation of TLR2-MyD88-mediated signaling pathway." (PMID 34136558, 2021). "TLR2, as an important pathogen pattern recognition receptor, plays a vital role in infection." (PMID 34222495, 2021). "In fact, a non-protective role was proposed for TLR2 as a result of increased expression of the gene for TLR-2 that was found after infection in susceptible (but not resistant) mice." (PMID 33668671, 2021). "In the case of a lethal mouse pneumovirus infection, it has been shown that Lactobacillus plantarum administered directly to the respiratory tract is able to protect mice against infection by mediating Lactobacillus plantarum engagement with TLR2 and NOD2 receptors." (PMID 35046936, 2021).
infection (continued). "Thus, either infection or an increase in plasma LPS resulted in either TLR2 and TLR4 up-regulation on monocytes or responsiveness of leukocytes to TLR2 and/or TLR4 ligands." (PMID 32378144, 2021). "However, we found that similar to Tnf transcription, TNF release upon Mtb infection was partially dependent upon MYD88 and TLR2 and very modestly increased upon infection with PDIM- or ESX-1-mutant Mtb." (PMID 34755600, 2021). "Importantly, during infection or inflammation, the microbial pathogen-recognizing TLR2 directly enhances the mobilization of LT-dependent Treg lymphatic migration." (PMID 33805271, 2021). "However, they fail to upregulate inflammatory mediators in response to infection with P. gingivalis and Toll-like receptor-2 (TLR2) agonists." (PMID 34031466, 2021). "Disseminated aerobic and anaerobic bacteria in the livers of WT and TLR2-deficient mice were also quantified with or without infection." (PMID 34322122, 2021). "The injection of Pam3CSK4 6 h after infection also improved survival, but it was inferior when compared to co-injection, suggesting that an early activation of TLR2 could be necessary for protection." (PMID 35046936, 2021). "Conversely this decrease may also contribute further during infection to the deposition of Aβ by the decreased TLR2 expression." (PMID 34154615, 2021). "We hypothesized that Tnf was part of a broader early TLR2-dependent transcriptional program; clustering genes across all infection conditions identified 17 genes with expression highly correlated with Tnf." (PMID 34755600, 2021). "Tlr2-/- mice have been shown to have increased Mtb dissemination to liver and spleen and a more rapid progression to death following infection." (PMID 34755600, 2021). "To test this hypothesis, we treated BMDMs and BMDCs overnight with the TLR2 agonist PAM3CSK4 (PAM) before infection with wild-type and Δhly L. monocytogenes and again analyzed transcript expression." (PMID 34555127, 2021). "Infection of PMA-treated THP-1 cells with MAP showed that the CD14+ cluster (classically differentiated macrophages) was most responsive to MAP, and this response was suggested to be associated with significantly higher TLR2 expression in that cluster." (PMID 34214113, 2021). "We hypothesized that overnight treatment with PAM3CSK4, a TLR2 agonist, would stimulate BMMs and increase MG levels, affecting infection dynamics of ΔgloA L. monocytogenes that are impaired for MG detoxification." (PMID 34407151, 2021). "Collectively, the results presented here show important limitations of using TIGFs to evaluate GF behavior under inflammatory conditions, and provide an independent confirmation that TLR2 is indispensable for GF activation in response to infection with P. gingivalis." (PMID 34031466, 2021). "Furthermore, it was found that when mice that had received TLR2–/– eosinophils were significantly better protected against CDT+ infection than WT mice." (PMID 34992590, 2021). "In addition, reports in the literature have shown that IL-10 and TLR2 knockout mice are highly resistant to infection by Leishmania spp." (PMID 34248935, 2021). "infections, TLR2, 4, 5, and 9 were mainly expressed, and these were the main concerns." (PMID 33829052, 2021). "Several studies have assessed the role of TLR2 in infection outcomes in mice." (PMID 34755600, 2021). "Both animals treated with β-glucan and LPS showed an increased expression of TLR2 in the kidneys 2 days post-infection, strongly suggesting that early TLR2 activation could be responsible for the survival observed." (PMID 35046936, 2021). "We next sought to understand whether the interaction between PDIM/ESX-1 and TLR2 contributes to infection outcomes in macrophages." (PMID 34755600, 2021). "Besides, although the expression of Foxp3 was upregulated after infection with A. fumigatus in the lung of TLR2−/− mice and WT mice, those of TLR2−/− mice were also reduced compared to WT mice (p < 0.05)." (PMID 34222495, 2021).
infection (continued). "It is noteworthy that TLR2 may be activated not only by bacterial cell wall lipoproteins in the context of infection but also by endogenous molecules (DAMPs) in the context of sterile inflammation." (PMID 34527000, 2021). "We thus hypothesized that infection with Mtb elicits a two-component TLR2-dependent response, and that the later component of the response is preferentially blunted by Mtb factors that damage the phagosomal membrane." (PMID 34755600, 2021). "Previous studies have shown that toll-like receptor (TLR) 4 plays positive roles in the induction of immune responses against Mtb and in eradication of the infection, while TLR2 contributes to host protection, immune evasion and immune regulation during chronic Mtb infection." (PMID 33202583, 2020). "MAP viability in macrophages treated with anti-TLR2 decreased to 63% but after 48 h infection." (PMID 33212859, 2020). "Moreover; significant association between TLR2 polymorphisms, TLR4 Arg753Gln polymorphisms and risk of severe infections in AML patients was documented." (PMID 33247673, 2020). "Infection of SJL mice with TMEV activates various cellular proteins via TLR2 and TLR3." (PMID 33069239, 2020). "TLR2, but not TLR9, was important for preventing S. aureus outgrowth during craniotomy infection, as revealed by the elevated bacterial burden in the brain, galea, and bone flap of TLR2 KO mice concomitant with global reductions in pro-inflammatory mediator production compared to WT animals." (PMID 32290861, 2020). "As for L.m. infections in THP-1 cells, a TLR2-TRIF pathway for IFN-I synthesis can be ruled out due to the lack of ISG expression upon the infection with the escape-deficient hly mutant strain which has been shown in this study." (PMID 33178195, 2020). "We therefore hypothesized that TLR2/CD14-dependent CME facilitates DENV entry to establish infection." (PMID 32576819, 2020). "For example, earlier work by us and others demonstrated that S. aureus biofilm infection in the periphery is not affected by TLR2 loss, whereas we show here that TLR2 is important for bacterial containment during S. aureus craniotomy infection." (PMID 32290861, 2020). "Therefore, we examined the functional importance of both receptors in bacterial containment during S. aureus craniotomy infection using TLR2 and TLR9 KO mice." (PMID 32290861, 2020). "Indeed, we observed that prolonged treatment (24 h) of THP-1 cells with TLR2 or TLR4 ligands prior to infection with Mtb decreased cell death and ASC speck formation to a similar extent as treatment with MCC950." (PMID 32385301, 2020). "During the decline of infection, in the 24 dpi group TLR2 expression increased." (PMID 32958053, 2020). "However, the mRNA levels for TLR4, tnf alpha, akr1, and TLR2 remained unchanged or increased after vaccination but decreased after infection." (PMID 32344637, 2020). "However, therapeutic targeting of either TLR2 or TLR4 from day two post-infection provided significant protection, suggesting that both TLR2 and TLR4 contribute to disease pathogenesis driven by damage-associated molecular patterns (DAMPs)." (PMID 32260457, 2020). "Furthermore, Nie shows that infection of mice with P. gingivalis induces the production of beta amyloid through the activation of CatB/NF-κB and the increase in the expression of TLR-2 and IL-1b." (PMID 32054121, 2020). "Collectively, the lack of overt changes in leukocyte recruitment in TLR2 KO animals suggests the existence of redundant chemotactic signals that are elicited in a TLR2-independent manner to promote leukocyte influx into the brain and galea during S. aureus craniotomy infection." (PMID 32290861, 2020). "High expression of TLR2 by DCs from BALB/c mice may support the early IL-27 expression after infection, which contributes to the attenuating of inflammation and promoting infection." (PMID 32849534, 2020). "Furthermore, our previous results showed that TLR2 was significantly up-regulated during PmCQ2 infection." (PMID 32922380, 2020).
infection (continued). "Notably, S. aureus produces staphylococcal superantigen-like protein 3 (SSL3) and TIR-containing protein (TirS) during infections, which interfere with TLR2 signaling and dampen appropriate TLR2 activation." (PMID 33256638, 2020). "Notably, the increase in TLR2 expression following in vitro-infection was in contrast to the data collected from our ex vivo samples but in line with previous findings." (PMID 32576819, 2020). "P. aeruginosa infection lead to TLR2 signalling 4 hours after infection only (p<0.01)." (PMID 33031374, 2020). "The anti-apoptotic effect against LPS infection of 5%LHFM_Cit-4mM is speculated to contribute by the TLR2 activating ability." (PMID 31949265, 2020). "We speculate with infection, the direct insult to the trophoblasts could be mediated by the Toll-like Receptor-2 (TLR-2), which is expressed on the trophoblastic membrane." (PMID 33553066, 2020). "Therefore, to identify the critical receptors upstream of MyD88, we investigated craniotomy infection in TLR2 and TLR9 knockout (KO) mice." (PMID 32290861, 2020). "Although outcomes of MRP14 signaling via TLR2 are still unknown, it is possible that each receptor has a different role and the expression pattern of the receptors at the infection sites changes the role of MRP14." (PMID 31961866, 2020). "In conclusion, we suggest that repeated infections, with exposure to microbial TLR2 agonists, may facilitate neurodegeneration in the hyper-vulnerable environment of the AD brain, an effect mediated by microglial toxicity." (PMID 32059733, 2020). "Another similarity between caspase-1 and TLR2 KO mice was the loss of bone flaps at later intervals, where 18% and 38% of caspase-1 KO animals had no bone flaps at days 21 or 28 post-infection, respectively." (PMID 32290861, 2020). "Specifically, we characterized the effect of nicotine on MyD88 in association with TLR2 in presence and absence of infection." (PMID 33212859, 2020). "The loss of either TLR2 or caspase-1 dramatically attenuated cytokine/chemokine production during S. aureus craniotomy infection, which supports the lack of this positive feedback loop and the inability to contain bacterial growth." (PMID 32290861, 2020). "Infection of macrophages with Mycobacteria increased TLR2 in gene and protein levels, respectively (MAP: 10.03 ± 0.64, MTB: 10.11 ± 1.02 vs. uninfected: 1.20 ± 0.67; p < 0.05 for gene), (MAP: 10.42 ± 0.20, MTB: 11.71 ± 0.42 vs. uninfected: 6.15 ± 1.06; p < 0.05 for protein)." (PMID 33212859, 2020). "To determine if MyD88 is the main adaptor protein in TLR2 signaling and to examine the effect of nicotine on MyD88 signaling and subsequent proinflammatory cytokine IL-8 in macrophage during infection, we measured expression of MyD88 and IL-8 following nicotine treatment of MAP-infected macrophages." (PMID 33212859, 2020). "To investigate this, we isolated PBMCs from DENV-infected patients during the acute phase of infection (n = 54) and 15 age-matched healthy donors (HD) and subsequently stained with an anti-human TLR2 antibody or a conjugated isotype-matched antibody as a control." (PMID 32576819, 2020). "In this work, combined hormones increased TLR2 MA (~25%), which was enhanced by infection (~100%)." (PMID 32605209, 2020). "Likewise, we observed that TLR2 is important to downmodulate α3 integrin levels after 24 h of infection." (PMID 33173103, 2020). "However, in longer periods of infection (24 h), P. brasiliensis downmodulates α3 integrin levels in direct contact- and TLR2-dependent manners." (PMID 33173103, 2020). "Therefore, our data demonstrate that TLR-2 and TLR-4 are indirectly associated with neutrophil migration because the lower levels of CXCL1 and CCL3 in KO animals’ infection site led to an impairment in neutrophil migration." (PMID 33193308, 2020).